L1CAM (L1 cell adhesion molecule)
Diseases named in the same sentence as L1CAM in open-access papers (continued):
Sharing a sentence is not in itself a finding about the gene and the disease.
endometrioid endometrial carcinomas (4 papers, 2013 to 2018). "The aim of this study was to analyse L1CAM expression in an independent series of stage I endometrioid endometrial carcinoma and to study the association of L1CAM expression with risk of relapse and death." (PMID 27488577, 2016). "The objective of this study was to determine the potential of L1 Cell Adhesion Molecule (L1CAM) to predict LVSI and its association with other risk factors in endometrioid endometrial carcinomas." (PMID 30557309, 2018). "L1CAM is highly associated with LVSI and could be used as a pre-operative predictor of lymph node involvement in endometrioid endometrial carcinomas." (PMID 30557309, 2018). "In this independent study sample, L1CAM failed to be a clinically relevant marker of poor prognosis in stage I endometrioid endometrial carcinoma." (PMID 27488577, 2016). "We previously reported that L1CAM was absent in the vast majority of endometrioid endometrial carcinomas (ECs) (type 1) but was strongly expressed in the more aggressive serous and clear-cell ECs (termed type 2)." (PMID 23530769, 2013).
endometriosis (4 papers, 2013 to 2025). The growth of functional endometrial tissue in anatomic sites outside the uterine body. "The neural cell adhesion molecule L1CAM is a transmembrane glycoprotein abnormally expressed in tumors and previously associated with cell proliferation, adhesion and invasion, as well as neurite outgrowth in endometriosis." (PMID 24324802, 2013). "L1CAM at the protein and mRNA levels was also found to be expressed in higher levels in endometriosis tissues than in healthy controls." (PMID 40870967, 2025). "An anti-L1CAM monoclonal antibody used in mice to treat endometriosis showed that this molecule indeed suppressed endometriosis growth." (PMID 40870967, 2025). "In fact, several features qualify L1CAM as a novel, attractive target molecule for antibody-based therapy in endometriosis." (PMID 24324802, 2013). "So far, the importance of the adhesion molecule L1CAM as a therapeutic target has been widely recognized in various tumor entities and recently suggested in endometriosis." (PMID 24324802, 2013). "Apart from its favorable transmembrane location, L1CAM was shown to be expressed in ectopic endometrium, especially in atypical lesions, and biologically important in endometriosis pathogenesis driving cell motility, invasion and growth promotion." (PMID 24324802, 2013). "Endometriosis was histologically confirmed and L1CAM was detected by immunohistochemistry." (PMID 24324802, 2013). "Nevertheless, it is worth mentioning that the normal distribution of L1CAM in adults is quite restricted and might support its suitability as therapeutic target for endometriosis (especially atypical endometriosis) in optimal doses." (PMID 24324802, 2013). "Given the role of L1CAM as a potential target for anti-cancer therapy and our preliminary data, we were prompted to investigate the in vivo effects of intraperitoneal anti-L1 mAb therapy using two distinct endometriosis mouse models." (PMID 24324802, 2013). "Notwithstanding, as L1CAM overexpression was shown to be particularly related with atypical endometriotic lesions, it is possible that anti-L1 mAb treatment might be most effective only for patients with atypical endometriosis." (PMID 24324802, 2013).
epilepsy (4 papers, 2015 to 2025). A brain disorder characterized by episodes of abnormally increased neuronal discharge resulting in transient episodes of sensory or motor neurological dysfunction, or psychic dysfunction. "Also, the abnormal expression of N-cadherin, like for L1CAM, has been associated with hippocampal synaptic remodeling and mossy fiber sprouting, which are key features in the pathogenesis of epilepsy." (PMID 40723903, 2025). "Taken together, L1CAM may represent a promising target in epilepsy research, offering potential insights into the underlying mechanisms of synaptic functions, neuroimmune regulation, and neural circuit remodeling." (PMID 40723903, 2025). "Since no studies on L1CAM in epilepsy have been carried out, we expected that its dysfunction would disrupt the excitatory–inhibitory synaptic balance and thereby increase seizure susceptibility." (PMID 40723903, 2025).
kidney cancer (4 papers, 2018 to 2022). Primary or metastatic malignant neoplasm involving the kidney. "The qRT-PCR results showed that lncRNA LINC01426 was upregulated while mRNA L1CAM was downregulated in kidney cancer tissues, which was consistent with the expression pattern in the TCGA database (P < 0.05)." (PMID 36072969, 2022). "It was previoulsy shown that PAX8 downregulation resulted in increased L1-CAM expression and enhanced migration of kidney cancer cells." (PMID 29435133, 2018).
malignant mesothelioma (4 papers, 2016 to 2025). A malignant neoplasm of the pleura or peritoneum, arising from mesothelial cells. "Another study reported that 13 out of 18 ATs expressed L1CAM protein, while 24 malignant mesotheliomas were negative, suggesting that L1CAM protein expression can serve as a marker for AT and help differentiate it from malignant mesothelioma." (PMID 41584583, 2025).
MASA syndrome (4 papers, 2021 to 2025). MASA syndrome (Mental retardation, Aphasia, Spastic paraplegia, Adducted thumbs) is a historical term used to describe a phenotype now considered to be part of the X-linked L1 clinical spectrum (L1 syndrome). "At birth, we suspected a condition linked to a variant in the L1CAM gene, in particular, the MASA syndrome." (PMID 34206215, 2021). "L1CAM is a causative gene for a spectrum of hereditary genetic disorders including MASA syndrome." (PMID 37943774, 2023). "The first diagnostic hypothesis was therefore of an L1CAM-related condition, MASA syndrome (MIM #303350), which is often associated with adducted thumb and has clinical manifestations largely overlapping with WHSUS." (PMID 34206215, 2021).
squamous cell carcinoma (4 papers, 2011 to 2019). A carcinoma arising from squamous epithelial cells. "In our cohort, L1CAM expression was higher in adeno(squamous) carcinoma (37%), when compared to squamous cell carcinoma (15%)." (PMID 29152102, 2017). "L1CAM protein expression was found in 25% of squamous cell carcinomas and 24% of adenocarcinomas and correlated with blood vessel invasion and metastasis (p < 0.05)." (PMID 21985405, 2011). "Furthermore, L1CAM expression (≥10%) was observed more frequently in adenocarcinoma (37%) and adenosquamous carcinoma (33%) than in squamous cell carcinoma (15%; squamous cell carcinoma vs. adeno(squamous) carcinoma: OR = 3.2, 95% CI 1.9 – 5.4, P <0.001)." (PMID 29152102, 2017).
cervical cancer (3 papers, 2017 to 2026). A primary or metastatic malignant neoplasm involving the cervix. "The aim of the present study was to determine the protein expression of L1CAM and its association with clinical parameters and patient survival in a large cohort of cervical cancer patients, as well as in a TCGA validation cohort." (PMID 29152102, 2017). "Here, we determined the prognostic significance of L1CAM in cervical cancer and its association with vimentin expression on tumor cells, indicative of EMT." (PMID 29152102, 2017). "In cervical cancer cell lines, such as HeLa, overexpression of L1CAM was significantly associated with differentiation." (PMID 29152102, 2017). "L1CAM might be a promising new prognostic marker for locoregional recurrences in cervical cancer, and its association with vimentin expression suggests that L1CAM might affect tumor aggressiveness, possibly through EMT." (PMID 29152102, 2017). "Differences in CDK15 and L1CAM L1 expression in cervical cancer tissues were compared across subgroups stratified by different clinicopathological characteristics, including age and International Federation of Gynecology and Obstetrics(FIGO) stage." (PMID 41994380, 2026). "RNAi-mediated knockdown of LICAM decreased the proliferation, migration and invasion of cervical cancer cells while over-expression of L1CAM increased proliferation, migration and invasion." (PMID 29152102, 2017). "Our data show that L1CAM expression (≥10%) was a strong independent predictor of worse locoregional recurrence-free survival in 372 cervical cancer patients (HR 2.62, 95% CI 1.33 – 5.17, P = 0.006)." (PMID 29152102, 2017). "Formalin-fixed, paraffin-embedded primary tumor samples from 372 cervical cancer patients were collected for immunohistochemical analysis of L1CAM expression." (PMID 29152102, 2017). "Based on the link found between macrophage infiltration and TGF-beta activation in the present cohort, further functional analyses are warranted and much needed to investigate the possible role of L1CAM in EMT in cervical cancer." (PMID 29152102, 2017). "Immunohistochemical staining of L1CAM in cervical cancer tissues was observed to be mainly membranous, accompanied in some cases by weak cytoplasmic staining." (PMID 29152102, 2017). "Consequently, CDK15 and L1CAM hold promise as novel prognostic biomarkers and potential therapeutic targets for cervical cancer." (PMID 41994380, 2026). "This is the first study reporting on the expression of L1CAM in cervical cancer specimens." (PMID 29152102, 2017). "In conclusion, L1CAM might be a promising new prognostic marker for locoregional recurrences in cervical cancer, independent of currently established prognostic markers." (PMID 29152102, 2017).
diabetes (3 papers, 2016 to 2022). "For example, STAT1 and L1CAM expressions were found to be jointly downregulated in diabetes-related skin disorders." (PMID 35003395, 2021).
endometrial tumor (3 papers, 2018 to 2021). "L1CAM expression is commonly observed in high-grade endometrial tumors (including serous and clear cell carcinomas) and is associated with tumor vascular invasion." (PMID 33672863, 2021). "The immunohistochemical (IHC) detection of L1CAM in endometrial tumor samples seems to be able to discriminate a subset of highly aggressive tumors with high risk of distant recurrences and to assess the risk of pelvic lymph-node involvement." (PMID 29980240, 2018). "The IHC detection of L1CAM in endometrial tumour samples is able to discriminate a subset of highly aggressive tumours with adverse clinical outcome and high risk of distant recurrences, and to assess the risk of pelvic lymph-node involvement." (PMID 29980240, 2018). "We then analyzed the protein levels of L1CAM and ANXA2 by ELISA in the purified EVs, known biomarkers with prognostic value in endometrial tumor tissue samples." (PMID 31842290, 2019).
esophageal squamous cell carcinoma (3 papers, 2020 to 2022). Esophageal squamous cell carcinoma (ESCC) is a type of esophageal carcinoma (EC) that can affect any part of the esophagus, but is usually located in the upper or middle third. "However, the link between L1CAM and the tumor microenvironment remains poorly understood in patients with esophageal squamous cell carcinoma (ESCC)." (PMID 33710805, 2021).
frontotemporal dementia (3 papers, 2020 to 2025). Frontotemporal dementia (FTD) comprises a group of neurodegenerative disorders, characterized by progressive changes in behavior, executive dysfunction and language impairment, as a result of degeneration of the medial prefrontal and frontoinsular cortices. "Goetzl and coworkers (2016) demonstrated that the levels of synaptophysin, synaptopodin, synaptotagmin-2, and neurogranin in L1CAM+ EVs were significantly lower in patients with frontotemporal dementia and AD than in controls." (PMID 38898538, 2024). "Moreover, the levels of cathepsin D, lysosome-associated membrane protein 1, and ubiquitinylated proteins in L1CAM+ EVs are significantly higher in AD patients than in healthy controls and patients with frontotemporal dementia, an Alzheimer-mimic disease." (PMID 38898538, 2024).
gallbladder cancer (3 papers, 2013 to 2017). "L1CAM expression in gallbladder carcinomas was significantly associated with high histologic grade, advanced pathologic T stage and clinical stage, and positive venous/lymphatic invasion." (PMID 24422715, 2013).
Hirschsprung disease (3 papers, 2010 to 2023). Hirschsprung disease (HSCR) is a congenital intestinal motility disorder that is characterized by signs of intestinal obstruction due to the presence of an aganglionic segment of variable extent in the terminal part of the colon. "RET, NRG1, and L1CAM genes are reported as pathological gene variants associated with the incidence of different variants of Hirschsprung's disease." (PMID 38169757, 2023). "In our particular case we could propose exactly the same pathogenic mechanism for the connection between the L1CAM gene and Hirschsprung disease in our patient carrying the duplication at Xq28." (PMID 20860806, 2010). "The presence of Hirschsprung disease in MDS, although rare, has also been suggested to be linked to dysregulated levels of the L1CAM gene (which can be implicated in Xq28 duplications) as L1CAM mutations have been detected in patients with X-linked hydrocephalus with Hirschsprung disease." (PMID 35313898, 2022). "Although a more comprehensive analysis of additional HSCR genes is warranted, our results support an involvement of L1CAM duplication in the pathogenesis of HSCR, and present evidence of a possible novel syndromic form of Hirschsprung disease." (PMID 20860806, 2010).
Insulin resistance (3 papers, 2021 to 2024). Increased resistance towards insulin, that is, diminished effectiveness of insulin in reducing blood glucose levels. "On the other hand, a relationship between the expression of IRS-1 in L1CAM+ EXOs and systemic insulin resistance was only found in healthy controls (HCs), and sex differences were reported in the serine-312 phosphorylation of IRS-1 in L1CAM+ EXOs in the MDD group." (PMID 33430399, 2021). "In vertebrates, weak expression of L1-CAM is found in adult islets of Langerhans, where the endocrine cells of the pancreas are found, and a single nucleotide polymorphism near the CHL1 locus, another L1 homolog, has been associated with insulin resistance." (PMID 34276554, 2021).
intrahepatic cholangiocarcinoma (3 papers, 2013 to 2020). A carcinoma that arises from the intrahepatic bile duct epithelium in any site of the intrahepatic biliary tree. "WFA has high affinity to the cancer biomarker L1 cell adhesion molecule (L1CAM) and has been employed for detecting intrahepatic cholangiocarcinoma (CC)." (PMID 32509848, 2020). "Another study reported cytotoxicity and anti-tumor activity of L1CAM chimeric antibody cA10-A3 in a mouse model of intrahepatic cholangiocarcinoma." (PMID 32429448, 2020).
lung adenocarcinoma (3 papers, 2022 to 2024). A carcinoma that arises from the lung and is characterized by the presence of malignant glandular epithelial cells. "The TAZ-ABL2-AXL signaling axis promotes the increased expression of a panel of brain metastatic targets, including L1CAM, required for lung adenocarcinoma brain metastasis." (PMID 37835395, 2023). "L1CAM high expression was found in 62.30% of brain metastases from lung adenocarcinoma and significantly correlated with brain metastasis number (p = 0.028) and Lung-molGPA score (p = 0.042)." (PMID 35525225, 2022). "In conclusion, the authors demonstrate that a subset of brain metastases from lung adenocarcinoma aberrantly expresses L1CAM." (PMID 35525225, 2022). "L1CAM is a novel independent prognostic factor for brain metastasis from lung adenocarcinoma after neurosurgical resection." (PMID 35525225, 2022). "The present study aimed to investigate the relationship between L1CAM expression in cranial metastatic lesions and clinicopathological parameters in the population of patients with brain metastases from lung adenocarcinoma after neurosurgical resection." (PMID 35525225, 2022). "A subset of brain metastases from lung adenocarcinoma aberrantly expresses L1CAM." (PMID 35525225, 2022). "Activated TAZ in lung adenocarcinoma cells elicits the expression of a panel of target genes that promote brain metastasis, including ABL2, AXL, and L1CAM." (PMID 37835395, 2023). "A role for the L1CAM (cell adhesion molecule 1)-mediated activation of YAP was shown to be required for the metastatic seeding and colonization of lung adenocarcinoma and breast cancer cells." (PMID 37835395, 2023). "The L1CAM expression in the primary lung lesion of each patient was not concurrently examined in this study because of the absence of lung adenocarcinoma samples, which is a limitation of the present study." (PMID 35525225, 2022). "However, no data of L1CAM are available for the brain metastases from lung adenocarcinoma, especially for the one with neurosurgical resection." (PMID 35525225, 2022).
Obesity (3 papers, 2016 to 2023). Accumulation of substantial excess body fat. "All of the tested variables, i.e. overweight/obesity, stage, features of the primary tumor, estrogen and progesterone receptor expression, L1CAM expression, and adjuvant therapy, were associated with cancer-related mortality in unadjusted analyses." (PMID 33232359, 2020).
oncocytoma (3 papers, 2023 to 2025). "Given the morphological and immunophenotypic overlap among eosinophilic renal tumors, we aimed to evaluate the diagnostic performance of L1CAM in differentiating LOT from oncocytoma, E-chRCC, and EVT in a multi-institutional cohort." (PMID 40805143, 2025). "L1CAM overexpression has been reported in many human carcinomas and correlated with metastasis, but rarely detected in chRCC (2%) or oncocytomas (8%) in a previous study." (PMID 37994665, 2024). "For instance, both LOT and E-chRCC are diffusely CK7-positive but differ in CD117 and L1CAM expression, while oncocytoma and EVT may resemble LOT morphologically yet lack both CK7 and L1CAM positivity." (PMID 40805143, 2025). "Importantly, sporadic ChRCCs and sporadic oncocytomas were further clustered into two distinct clusters, and differentially expressed genes (DEGs) analysis identified L1CAM, FOXI1 and its downstream gene, ATP6V0D2 as molecular markers for these distinct clusters (Group1 and 2)." (PMID 37182269, 2023). "L1CAM exhibited distinct staining patterns between the LOT cohort and the other three groups (oncocytoma, E-chRCC, and EVT), making it particularly valuable in challenging cases with unusual histologic or IHC features." (PMID 40805143, 2025). "L1CAM showed 100% sensitivity (10/10; 95% CI: 69.2–100%) and 100% specificity (44/44; 95% CI: 92.0–100%) in distinguishing LOT from the other eosinophilic renal neoplasms in this cohort (oncocytoma, E-chRCC, and EVT)." (PMID 40805143, 2025). "Furthermore, our study is the first to demonstrate the reliability of L1CAM in distinguishing LOT from other eosinophilic renal tumors, such as oncocytomas and EVT." (PMID 40805143, 2025). "All 18 oncocytoma cases showed absence of L1CAM expression and strong uniform LINC01187 expression." (PMID 37994665, 2024). "In contrast, all cases from the other cohorts (oncocytoma, E-chRCC, and EVT) were completely negative for L1CAM." (PMID 40805143, 2025).
primitive neuroectodermal tumor (3 papers, 2013 to 2018). A malignant neoplasm that originates in the neuroectoderm. "SSEA-5 exhibited strong immunoreactivity in embryonal carcinoma and primitive neuroectodermal tumors, while L1CAM was much less intense." (PMID 26317026, 2013).